RPE65 (retinoid isomerohydrolase RPE65)
Diseases named in the same sentence as RPE65 in open-access papers (continued):
Sharing a sentence is not in itself a finding about the gene and the disease.
Visual impairment (2 papers, 2018 to 2024). "However, LCA-CEP290 is associated with far more profound visual impairment at an earlier age (from birth/early infancy) compared with RPE65 deficiency; therefore, visual cortical plasticity may be a more significant limitation to treatment response." (PMID 29398085, 2018). "Rodent (Crb1, Lrat, Mertk, Rpe65, and Rpgrip1), avian (Gucy2D), and canine (Rpe65) models for LCA and profound visual impairment have been successfully corrected employing adeno-associated virus or lentivirus-based gene therapy." (PMID 39055259, 2024).
biotinidase deficiency (1 paper, 2025). A late-onset form of multiple carboxylase deficiency, an inborn error of biotin metabolism that, if untreated, is characterized by seizures, breathing difficulties, hypotonia, skin rash, alopecia, hearing loss and delayed development. "Less frequently, variants in heterozygosity were found in RPE65 (n = 21, 0.53%), GAA (n = 20, 0.50%), BTD (n = 15, 0.38%), and TRDN (n = 12, 0.30%), associated with RPE65-related retinopathy, Pompe disease, biotinidase deficiency, and catecholaminergic polymorphic ventricular tachycardia." (PMID 40332002, 2025).
geographic atrophy (1 paper, 2017). "As illustrated by RPE65 staining, cellular damage similar to geographic atrophy can be observed in PEG-400-induced retinal damage." (PMID 28961167, 2017).
hamartoma (1 paper, 2018). A benign and excessive tumor-like growth of mature cells and normal tissues which grow in a disorganized pattern. "RPE65 expression was detected in a punctate fashion in the RPE of P21 wild-type and Pten cKO (H′) retinas, including in the cell layer overlying the hamartoma and in the retinal rosettes within this structure." (PMID 29716894, 2018).
Hyperglycemia (1 paper, 2018). An increased concentration of glucose in the blood. "This compound neutralized the hyperglycemia-elicited reduction of the retinoid visual cycle components of RPE65, LRAT, RDH5, CRBP, CRALBP, IRBP, and STRA6 in retina." (PMID 30096827, 2018).
macular holes (1 paper, 2024). A hole in the macula of the retina. "We also report the successful surgical management of the complication and our considerations of the possible concurrent risk factors for macular hole occurrence in this atypical RPE65 phenotype." (PMID 39062658, 2024).
oculocutaneous albinism (1 paper, 2022). Oculocutaneous albinism (OCA) describes a group of inherited disorders of melanin biosynthesis characterized by a generalized reduction in pigmentation of hair, skin and eyes and variable ocular findings including nystagmus, reduced visual acuity and photophobia. "Individuals with TYR-associated oculocutaneous albinism and those with RPE65-associated disease showed significantly increased odds for longer ALs (≥26 mm) and also for shorter ALs (≤22 mm)." (PMID 35704304, 2022).
oligodendroglioma (1 paper, 2023). A well-differentiated (WHO grade II), diffusely infiltrating neuroglial tumor, typically located in the cerebral hemispheres. "Interestingly, RPE65 was lowest in oligodendroglioma compared to other pathological types." (PMID 37183261, 2023).
retinal lattice degenerations (1 paper, 2020). "The purpose of this present study was to perform RPE65 and CK immunostaining on retinal tissues containing specimens of retinal lattice degenerative lesions collected during vitreous surgery, and to report our novel findings on the pathogenesis of retinal lattice degeneration." (PMID 33027920, 2020). "In this present study, retinal lattice degenerations were intraoperatively harvested from patients with rhegmatogenous retinal detachment, and were then used to perform immunostaining with GFAP, which is a glial cell marker, and CK and RPE65, which are retinal pigment epithelial markers." (PMID 33027920, 2020).
teratoma (1 paper, 2019). A non-seminomatous germ cell tumor characterized by the presence of various tissues which correspond to the different germinal layers (endoderm, mesoderm, and ectoderm). "The RPE65-hiPSCs presented typical morphological features with normal karyotype, expressed pluripotency markers, and developed teratoma in NOD-SCID mice." (PMID 31572124, 2019).
uveal melanoma (1 paper, 2025). A melanoma derived from melanocytes of the uveal tract. "The expanded choroid, ciliary body, and iris were positive for S100b and negative for RPE65, consistent with the development of uveal melanoma." (PMID 39804140, 2025).
uveitis (1 paper, 2022). An inflammatory process affecting a part of or the entire uvea. "In another LCA clinical trial (NCT02781480, Phase 1/2) delivering the RPE65 gene via the AAV2/5 vector, uveitis developed in one out of three patients in the low dose group, all three patients in the intermediate dose group and in two out of three patients in the high dose group." (PMID 36145721, 2022). "However, 75% of the eyes that received AAV-RPE65 developed uveitis while the sham-injected and the AAV-GFP controls did not, implying that the uveitis was in response to the RPE65 gene/protein product." (PMID 36145721, 2022).
viral infection (1 paper, 2019). "RPE65-positive RPE cells and GFAP-positive glial cells were the main targets of viral infection." (PMID 31291924, 2019).
vitamin A deficiency (1 paper, 2025). Deficiency of vitamin A due to malnutrition, malabsorption, or dietary lack. "While this mechanism remains valid, especially in models such as Lrat- or Rpe65-deficient mice, our results extend this paradigm by showing that vitamin A deficiency affects RPE barrier integrity and immune privilege." (PMID 41135684, 2025).
retinopathy (34 papers, 2015 to 2025). "Dominant RPE65-related retinopathy, however, due to Irish founder variant p.(D477G), is extremely rare." (PMID 40386434, 2025). "Our study provides strong genetic, clinical, molecular and functional evidence for a novel, adult-onset dominant RPE65-associated retinopathy due to founder variant p.(E519K)." (PMID 40386434, 2025). "In the current study, we established a molecular genetic diagnosis of “RPE65-associated retinopathy” in 5.3% of patients with a confirmed IRD diagnosis." (PMID 38002999, 2023). "The most common pathogenic variants in patients with RPE65-associated retinopathy from the Russian Federation were c.304G>T/p.(Glu102*), c.370C>T/p.(Arg124*), and c.272G>A/p.(Arg91Gln), comprising 41.8% of all affected chromosomes." (PMID 38002999, 2023). "Later, another case of RPE65-associated retinopathy caused by maternal uniparental isodisomy was described in the literature." (PMID 38002999, 2023). "In the cohort of patients with RPE65-associated retinopathy from the USA and Europe, this variant was the most common, with a prevalence of 22.5%." (PMID 38002999, 2023). "The patients’ age at the moment of their molecular genetic diagnosis of “RPE65-associated retinopathy” varied from 4 months to 50 years." (PMID 38002999, 2023). "Proof-of-concept studies in murine and canine models have shown the potential of gene therapy for RPE65-associated retinopathy, which has led to the initiation of human clinical gene-therapy trials." (PMID 37108642, 2023). "The prevalence of c.271C>T and c.11+5G>A in Russian patients with RPE65-associated retinopathy was 3.45% and 5.17%, respectively." (PMID 38002999, 2023). "RPE65-associated retinopathies became the first group of hereditary ophthalmological disorders with approved gene therapy; therefore, the RPE65 gene came under the close attention of researchers from around the world." (PMID 38002999, 2023). "We assessed 3 of these patients further, carrying the p.Arg91Trp mutation, which has been described previously in RPE65 retinopathy." (PMID 31925606, 2020). "In mice, the availability of RPE65 was shown to modulate retinal susceptibility to light damage; higher concentrations causing a more severe retinopathy (due to a faster regeneration and, thus, increased availability of rhodopsin)." (PMID 27355622, 2016). "Here, we report the discovery, replication and characterization of a novel dominant retinopathy caused by RPE65 variant p.(E519K), identified in 83 individuals of European ancestry across IRD registries (Belgian discovery cohort, n=2,873; replication cohort, n=18,796)." (PMID 40386434, 2025). "Most children with RPE65-associated retinopathy present with severe night blindness from birth." (PMID 39598155, 2024). "However, the prevalence of RPE65-associated retinopathy in Denmark and India differs from the worldwide average, reaching 16% and 16.6%, respectively." (PMID 38002999, 2023). "Thus, the obtained results confirm the data presented in previous studies: missense replacements in the RPE65 gene are a common cause of RPE65-associated retinopathies." (PMID 38002999, 2023). "The current study is aimed at the evaluation of the prevalence of RPE65-associated retinopathy in the Russian Federation, the characterization of known variants in the RPE65 gene, and the establishment of the specificities of the mutation spectrum in Russian patients." (PMID 38002999, 2023). "The positive results in both safety profiles and clinical endpoints in these trials have resulted in the approval of voretigene neparvovec as the first FDA-approved gene therapy for patients with RPE65-associated retinopathy, which is now commercially available as Luxturna®." (PMID 37108642, 2023). "Indeed, RPE65 mutations account for only a small proportion of inherited retinopathies." (PMID 37177842, 2023). "ABCA4 and RPE65 have also been proposed as genetic modifiers that result in a more severe phenotype in PRPH2 retinopathy." (PMID 41009962, 2025).
retinopathy (continued). "Overall, our work provides strong genetic, clinical, molecular and functional evidence for a novel dominant RPE65 retinopathy in multiple families in Europe and North America due to a Belgian founder variant." (PMID 40386434, 2025). "Several candidate susceptibility genes including RP1L1, RPGR, RPE65 and CCDC66 were identified to be associated with CQ/HCQ retinopathy." (PMID 38548946, 2024). "In this study, several candidate susceptibility genes including RP1L1, RPGR, RPE65 and CCDC66 were identified to be associated with CQ/HCQ retinopathy via exome sequencing and genome-wide association study." (PMID 38548946, 2024). "Several candidate genes associated with CQ/HCQ retinopathy were found with exome sequencing, including RP1L1, RPGR, RPE65, CACNA2D4, EYS, RP1, IMPG1 and ABCA4." (PMID 38548946, 2024). "Several candidate genes associated with CQ/HCQ retinopathy were found, including RP1L1, RPGR and RPE65, with a difference of affected percentage over 50% in mutation between the case and control groups." (PMID 38548946, 2024). "Gene therapy is now a realistic option for patients with molecularly confirmed biallelic RPE65-retinopathy, which aims to restore protein expression via adeno-associated viral (AAV) vector delivery of healthy RPE65 cDNA." (PMID 36498452, 2022). "Currently, there are no effective treatments available to address the progression of inherited retinal disorders such as RP, except for RPE65 gene therapy (voretigene neparvovecrzyl, Luxturna; Spark Therapeutics)." (PMID 34206804, 2021). "Here, we describe the discovery, replication, clinical, molecular and functional characterization of a novel AD RPE65-related retinopathy in multiple families in Europe and North America due to a Belgian founder variant c.1555G>A, p.(Glu519Lys), hereafter referred to as p.(E519K)." (PMID 40386434, 2025). "RPE65-associated retinal disorders are the first for which human gene therapy has become available, with many other retinal dystrophies, including LRAT-associated retinal disorders, to follow." (PMID 34281288, 2021). "The RPE65 gene was included on the basis that an FDA-approved gene therapy now exists for biallelic RPE65-retinopathies and that patients may derive additional benefit from earlier detection and therapeutic intervention." (PMID 34073611, 2021). "Given the success of the gene therapy treatment of biallelic RPE65 retinopathies with Luxturna, an AAV-based therapy, it is interesting to speculate whether the therapy might have any utility for monoallelic dominant RPE65 cases." (PMID 31963381, 2020). "Additionally, patients with RPE65-related retinopathy may also present with SECORD/EOSRD." (PMID 39598155, 2024). "Our approach was to develop an oral non-retinoid, small molecule inhibitor of RPE65 (emixustat) and assess treatment effects in mouse models of light-mediated retinal damage, aberrant lipofuscin accumulation, and oxygen-induced retinopathy." (PMID 25970164, 2015).
tumor (6 papers, 2023 to 2025). "Importantly, protein and mRNA expression of RPE65 was significantly up-regulated in tumor cells in different cohorts." (PMID 37183261, 2023). "Moreover, mRNA expressions of CA14, RPE65, IGSF1, SLC18 A2 and CPNE6 were significantly lower in PCa samples compared to benign samples, while HJURP, COMP, KRTAP5-1, VGF, SSTR1, LINC01612, NAALADL2-AS2, AMH and ARHGDIG were elevated in tumor samples (p < 0.05)." (PMID 40592939, 2025).
cancer (3 papers, 2022 to 2023). A tumor composed of atypical neoplastic, often pleomorphic cells that invade other tissues. "In the 8-mRNA signature (KCNJ18, RPE65, GRIA1, LCN15, C11orf21, ANXA13, FSIP2 and KRT76), the expressions of some mRNAs have been reported to have significant associations with the survival in some cancers." (PMID 35675043, 2022).
degenerative diseases (2 papers, 2022 to 2024). "Apart from cell metabolism, several pathways related to DNA (cell cycle) and RNA (spliceosome) functions, protein translation (Aminoacyl-tRNA biosynthesis), as well as neurodegenerative diseases, were also distinctly regulated in the Rpe65−/− mouse retinas." (PMID 39389360, 2024). "The present study describes RPE65-61, a novel, non-retinoid compound, as an inhibitor of RPE65 (a key enzyme in the visual cycle), intended to modulate the excessive activity of the visual cycle to protect the retina from harm degenerative diseases." (PMID 36227868, 2022).
genetic disease (2 papers, 2016 to 2023). "Through our analysis of CFH, rhodopsin, and RPE65, we were able both to draw conclusions relating to critical residues in protein structures and to predict misfolding-causing mutations in genetic disease." (PMID 27905547, 2016). "Among these, Luxturna, the first approved gene therapy for a genetic disease, is a recombinant AAV 2 vector containing human RPE65 complementary DNA that enables RPE cells to produce the retinoid isomerohydrolase RPE65." (PMID 38137442, 2023).
infection (2 papers, 2020). The state of being infected such as from the introduction of a foreign agent such as serum, vaccine, antigenic substance or organism. "We transduced iRPE cells with a multiplicity of infection (MOI) of 1 or 5 and measured RPE65 mRNA level and the lentiviral genome relative copy number by qPCR five days later." (PMID 32483256, 2020).
RPE65 also shares sentences with these, for which no sentence is quoted: hemophilia B (4 papers); X-linked retinoschisis (4); Chorioretinal atrophy (3); autism (2); congenital retinoschisis (2); hyperopia (2); Stargardt disease (2); acute lymphoblastic leukemia (1); Adult onset (1); AIDS (1); amblyopia (1); Astigmatism (1); B-cell precursor acute lymphoblastic leukemia (1); beta thalassemia (1); bladder urothelial carcinoma (1); blue cone monochromacy (1); breast carcinoma (1); catecholaminergic polymorphic ventricular tachycardia (1); Childhood onset (1); ciliopathy (1); diabetic retinopathy (1); Dravet syndrome (1); Dyschromatopsia (1); enhanced S-cone syndrome (1); episodic ataxia type 2 (1); gastric cancer (1); glaucoma (1); glioma (1); gyrate atrophy (1); haemophilia (1).
A further 30 diseases each share a sentence with RPE65 in 1 paper.